CCL1 (C-C motif chemokine ligand 1)
Diseases named in the same sentence as CCL1 in open-access papers (continued):
Sharing a sentence is not in itself a finding about the gene and the disease.
melanoma (10 papers, 2015 to 2023). A malignant, usually aggressive tumor composed of atypical, neoplastic melanocytes. "Other chemokine ligands important during the metastatic process include the CXCR3 ligand CXCL10 (in melanoma and colorectal cancer), the CXCR4 ligand CXCL12 (in multiple types of cancer) and CCL1 (in melanoma)." (PMID 37744339, 2023). "As we showed, melanoma exosome-delivered miR-125b-5p reinforces the activation of M1 macrophages through the induction of CCL1, CCL2, and IL-1β expression, thus contributing to myeloid cell recruitment and cancer-associated inflammation." (PMID 32079286, 2020). "We showed that treatment with melanoma-derived exosomes or miR-125b-5p overexpression induced a morphological switch of M1 macrophages together with an enforced expression of IL-1β, CCL-1, CCL2, and CD80 (B7-1)." (PMID 32079286, 2020). "CM derived from bcl-2 overexpressing melanoma cells treated with IL-1β blocking antibody caused a strong inhibition of M2 macrophage polarization, resulting in significant reduction of M2 (CD206, CCL1, CCL22) and induction of M1 (COX-2 and IL-12) markers." (PMID 32269145, 2020). "As compared with H1299 control cells and similar to melanoma cells, CM from H1299 cells overexpressing bcl-2 promoted M2 polarization of M-DM, associated with increased expression of M2 (CD206, IL-10 and CCL1) and reduction of M1 (COX-2 and IL-12) markers and increased THP-1 cell migration." (PMID 32269145, 2020). "In addition, melanoma exosome-delivered miR-125b-5p contributes to the phenotypic transformation of macrophages with the induction of C-C motif chemokine ligand 1(CCL1), CCL2, and IL-1β expression, thus leading to myeloid cell recruitment and cancer-associated inflammation." (PMID 36612077, 2022). "Regarding chemokines, CCL1, CCL17, CCL22 and CCL23, were significantly increased in FGFR Mut melanoma (all P < 0.05)." (PMID 36426352, 2022). "Using qRT-PCR we observed an increased expression of IL-1β, CCL1, CCL2, and CD80 in transfected M1 macrophages, similarly to in M1 macrophages co-cultured with melanoma cells or treated with melanoma-derived exosomes." (PMID 32079286, 2020). "Recently, the chemokine CCL1 and its receptor CCR8 were demonstrated to be important for melanoma cell entry into TDLNs." (PMID 29527513, 2018). "CCL1 and CCL22, the main ligands for CCR8 and CCR4, respectively, have been shown to be upregulated both at the gene and protein levels in the TME of melanoma, suggesting that melanoma cells are able to actively recruit T-regs." (PMID 34830780, 2021). "CCL1 is produced by SCS LECs and mediated entry of CCR8+ melanoma cells into LNs." (PMID 29527513, 2018).
pulmonary fibrosis (10 papers, 2020 to 2025). Chronic progressive interstitial lung disorder characterized by the replacement of the lung tissue by connective tissue, leading to progressive dyspnea, respiratory failure, or right heart failure. "Follow-up experiments corroborate these findings, demonstrating that targeting the CCL1–AMFR axis significantly ameliorates pulmonary fibrosis." (PMID 40988754, 2025). "Liu and colleagues showed CCL1 promotes pulmonary fibrosis development through the activation of the AMFR–Ras–ERK–p70S6K signaling pathway." (PMID 40626890, 2025). "Chemokines, such as CXCL12, CCL1, and CCL18, are implicated in pulmonary fibrosis, acting as chemoattractants by combining with the chemokine receptors, and yet the role of CXCL16 and its receptor remain poorly understood." (PMID 38789926, 2024). "Alveolar macrophages and CD4+ T cells secrete CCL1, which promotes the differentiation of lung fibroblasts into myofibroblasts and contributes to pulmonary fibrosis." (PMID 37122736, 2023). "Administration of a CCL1-blocking antibody alleviates the severity of this kind of lung fibrosis by suppressing infiltration of inflammatory cells into the lungs." (PMID 36830702, 2023). "Neutralizing CCL1 or inhibiting CCL1 signaling reduces pulmonary fibrosis in vitro and in vivo, indicating that CCL1 is a potential therapeutic target for IPF." (PMID 37122736, 2023). "In mice, hMSC administration exacerbated lung fibrosis through persistent Ccl1 up-regulation." (PMID 39768150, 2024). "Expression of chemokines and chemokine receptors was different between the two organs, and we reasoned that continuous upregulation of CCL1 in the lungs induced by hMSCs could be related to pulmonary fibrosis with eosinophilia and airway inflammation." (PMID 32586381, 2020). "Moreover, treatment with CCL1-blocking Ab also reduced pulmonary fibrosis induced by hMSCs as compared with control Ab-treated mice." (PMID 32586381, 2020). "During pulmonary fibrosis, alveolar macrophages secrete multiple chemokines such as CCL18 and CCL1, which directly activate pulmonary fibroblasts and stimulate collagen production." (PMID 37122736, 2023). "For example, an anti-CCL1 monoclonal antibody ameliorated BLM- and hMSC-induced lung fibrosis in mice, and blockade of CCL3 with a monoclonal antibody or a CCL3-binding protein (evasin-1) attenuated PF in BLM mice." (PMID 36830702, 2023). "The chemokine CCL1 activates the AMFR-SPRY1 pathway, which facilitates differentiation of pulmonary fibroblasts into myofibroblasts and drives pulmonary fibrosis." (PMID 36479666, 2023). "Importantly, heightened activation of the CCL1–AMFR pathway in lung tissue drives both inflammatory responses, EMT and ECM deposition, uncovering a promising therapeutic avenue against pulmonary fibrosis." (PMID 40988754, 2025). "Although other chemokine-receptor pairs, such as CCL1, CCL8, and CCR8, garnered our attention, these findings suggest the intriguing possibility that the CXCR6-CXCL16 axis may play a role in specific immune cell recruitment and contribute to the pathogenesis of pulmonary fibrosis." (PMID 38789926, 2024).
atherosclerosis (7 papers, 2019 to 2025). A disease characterized by the build-up of fatty material and calcium deposition in the arterial wall resulting in partial or complete occlusion of the arterial lumen. "Inhibition of CCL1 promotes atherosclerosis and higher risk of cardiovascular events in mice." (PMID 36012110, 2022). "In the studies, increased expression of another representative of this group of regulatory molecules was found: chemokine (C-C motif) ligand 1 (CCL1) in the aorta of mice prone to atherosclerosis, in addition, CCL1 provided recruitment of leukocytes to the lesion." (PMID 37047399, 2023).
Allergy (6 papers, 2018 to 2025). An allergy is an immune response or reaction to substances that are usually not harmful. "Although no further evidence supports the involvement of CCL1 derived from the airway mucosal epithelium in allergic reactions in AR pathogenesis, our results indirectly suggest that CCL1 derived from NECs has a regulatory effect on Tregs." (PMID 40051629, 2025). "It is well known that Th2-related chemokines including CCL-1 are strongly related to the pathogenesis of allergic diseases." (PMID 36286030, 2022). "Previous studies have suggested that CCL1 may play a role in lymphocyte recruitment in allergic disease." (PMID 40051629, 2025). "In our research, we found that 4-PSB-2 suppressed CCL-1 expression in monocytes, which indicates the potential role of 4-PSB-2 in treating allergic diseases and asthma." (PMID 36286030, 2022). "Another study on bile duct sclerosis suggested that IgG-associated CCL1 chemotaxis of Th2 and Foxp3+ Treg cells occurs via the CCL1/CCR8 pathway, although these studies did not focus on airways and allergies." (PMID 40051629, 2025). "In this study, we first confirmed that 4-PSB-2 suppressed LPS-induced CCL-1 expression, and this result further indicated that 4-PSB-2 may have a potential role in treating or preventing allergic diseases." (PMID 36286030, 2022). "Interestingly, M2b macrophages, induced by IgG immunoglobulin complexes and LPS, upregulate IL-10 and chemokine (C-C motif) ligand 1 (CCL1) expression and have been reported in the context of both, allergy as well as cancer." (PMID 32708690, 2020). "did provide a proof that acteoside could alleviate inflammatory response by down-regulating the expression of CCL1, CCL2, CCL3 and CCL4 in allergy." (PMID 29708439, 2018).
Sepsis (6 papers, 2012 to 2026). Sepsis is defined as life-threatening organ dysfunction caused by a dysregulated host response to infection. "Beyond sepsis, Ccl1 and Tregs are implicated in diverse inflammatory diseases, like autoimmune disorders, chronic inflammatory conditions and cancer." (PMID 40254698, 2025). "This evidence verified that Alkbh5 mediates RNA degradation of Ccl1 to reduce Treg recruitment to the inflammation site, thus reducing inflammation resolution and aggravating sepsis‐associated ALI." (PMID 40254698, 2025). "This study suggests that Alkbh5 plays a significant pathological role in sepsis‐associated ALI by mediating m6A‐dependent Ccl1 mRNA degradation, which aggravates tissue damage and inflammation by reducing Treg recruitment." (PMID 40254698, 2025). "The findings from this study suggest that Alkbh5‐mediated m6A demethylation plays a crucial role in modulating the inflammatory response in sepsis‐associated ALI by affecting Ccl1 mRNA stability and Treg dynamics." (PMID 40254698, 2025). "Overall, these results suggest that Alkbh5 exacerbates sepsis‐induced lung injury by destabilising Ccl1 mRNA via m6A demethylation, leading to reduced Treg infiltration." (PMID 40254698, 2025). "Conversely, targeting Alkbh5 or supplementing Ccl1 could offer therapeutic benefits in managing sepsis‐induced lung injury." (PMID 40254698, 2025). "Additionally, CCL1 levels inversely correlated with organ failure severity in sepsis patients." (PMID 42091942, 2026). "CCL1 shows potential to serve as a biomarker to differentiate sterile and non-sterile inflammation in sepsis and acute pancreatitis." (PMID 42091942, 2026). "What's more, in sepsis or aseptic inflammation, overexpressed TLR4 was related to the increased production of CCL1 and CXCL8 in order to recruit monocytes to the sites of infection 34, which was contrary to the inhibited chemotaxis of TLR4high monocytes in our patients with heatstroke." (PMID 40084252, 2025). "In sepsis‐induced ALI, the interaction between Ccl1 and Tregs is particularly complex." (PMID 40254698, 2025). "Indeed, we detected lower levels of CCL1, CXCL8 and CCL3 in plasma from heatstroke patients than in plasma from sepsis patients." (PMID 40084252, 2025). "Decreased CCL1 levels, but not CCL22, distinguished acute pancreatitis from sepsis at all time points." (PMID 42091942, 2026).
asthma (5 papers, 2010 to 2024). "In asthma, CCL1 is thought to play a role in recruiting inflammatory cells to the airways, leading to airway inflammation and hyperresponsiveness." (PMID 38361503, 2024). "We have used two reagents, a highly selective monoclonal antibody to CCR8 developed by ICOS Corporation and fluorescently labelled CCL1 (Millennium Pharmaceuticals), to study the involvement of CCL1 and its receptor CCR8 in asthma." (PMID 20455898, 2010). "The researchers found that the expression of mRNA-encoding TSLP, TARC/CCL17, MDC/CCL22 and IP-10/CXCL10, other than I-TAC/CXCL11 and I-309/CCL1, were significantly increased in severe asthma and COPD patients compared to the non-smoking control group." (PMID 34301307, 2021). "Similarly, two studies have found an increase in CCL1 in asthma, whereas others have not." (PMID 20455898, 2010).
pulmonary TB (5 papers, 2012 to 2023). "When considering combinations of biomarkers from previous studies, the existing pulmonary TB biosignature of CRP and CCL1 performed well in the current study, achieving an AUC of 0.95 compared to 0.90 in the original test set of suspected pulmonary TB." (PMID 34868023, 2021). "For the existing two-biomarker adult pulmonary TB-derived signature, CRP contributed significantly to the model (p < 0.001) but CCL1 did not (p = 0.91)." (PMID 34868023, 2021). "In the current study, CCL1 was no longer significantly different between spinal TB and mechanical back pain in subgroups without HIV infection or of similar age range and it is possible that this analyte has somewhat less utility for distinguishing spinal TB than pulmonary TB." (PMID 34868023, 2021).
Stroke (5 papers, 2020 to 2022). Sudden impairment of blood flow to a part of the brain due to occlusion or rupture of an artery to the brain. "Astrocytes increase IL-33 and CCL1 levels in response to stroke, and IL-33 is thought to promote the proliferation of Treg cells after stroke." (PMID 35743941, 2022). "Of note, the AUCs for GDF-15, D-dimer, ADAMTS13, CCL2/MCP-1, IL-4, CC4b, IL-7, ferritin, SAA, CCL1/I-309 and IL-10 were ≥0.75 in indicating stroke amongst children with TBM." (PMID 33930055, 2021). "Even though CCL1 is a chemokine that is secreted primarily by T cells, monocytes, and mast cells, it is also produced by brain astrocytes and mediates the chemotaxis of T regulatory cells during stroke." (PMID 32098620, 2020). "Astrocytes increase the level of IL-33 and CCL1 in response to stroke." (PMID 32174916, 2020). "CCL1 and CCL2 serve as early chemoattractants in stroke lesions, encouraging the infiltration by immune cells." (PMID 35912857, 2022). "The administration of CCL1, which binds to CCR8, increases the amount of Treg cells and promotes recovery after stroke." (PMID 32174916, 2020). "Moreover, Il10-KO CD8+ TRL–treated mice exhibited increased brain expression of IL-6, CCL1, and CCL2 after stroke compared with WT CD8+ TRL–treated mice." (PMID 35912857, 2022).
chronic obstructive pulmonary disease (4 papers, 2014 to 2023). A chronic and progressive lung disorder characterized by the loss of elasticity of the bronchial tree and the air sacs, destruction of the air sacs wall, thickening of the bronchial wall, and mucous accumulation in the bronchial tree. "Single-nucleotide polymorphisms in the chemokine CCL1 gene are associated with exacerbation of chronic obstructive lung disease." (PMID 27536524, 2016). "Prior to this study, we demonstrated that single-nucleotide polymorphisms (SNPs) in the CCL1 gene are associated with chronic obstructive pulmonary disease (COPD) exacerbation, that is mainly caused by respiratory tract infection and induces acute worsening of symptoms from the usual stable state." (PMID 27536524, 2016). "In chronic obstructive pulmonary disease (COPD) patients, CCL1 gene variants are associated with acute exacerbations (AEs), which are a major cause of morbidity and mortality in this chronic disease." (PMID 36830702, 2023). "For example, decreased expression of the ARE binding protein AUF-1 in chronic obstructive pulmonary disease (COPD) patient samples leads to stabilization of IL-6, CCL2, CCL1 and CXCL8 mRNA." (PMID 33806254, 2021). "Although CCL1 is not the primary chemokine secreted into the peritoneal cavity during laparotomy in humans, inflammatory macrophages in lung tissue from patients with chronic obstructive pulmonary disease (COPD) express high levels of CCR8." (PMID 24714157, 2014).
diabetes (4 papers, 2020 to 2024). "It has also been shown that CCL1 is a crucial factor in the pathogenesis of neuropathic pain induced by diabetes." (PMID 32691345, 2020). "Importantly, the expression of chemokines such as CXCL1 and CCL1 is modulated by NF-κB in many diseases such as cancer, diabetes, and neurological disorders." (PMID 39587693, 2024).
endometriosis (4 papers, 2012 to 2025). The growth of functional endometrial tissue in anatomic sites outside the uterine body. "Notably, innate cellular chemoattractants (IL-12, I-309/CCL1, Eotaxin, MCP-1, IL-6, IL-8, and IFN-γ) were almost exclusively elevated in endometriosis patients with the sole exception of the neutrophil chemoattractant ENA-78/CXCL5." (PMID 31333337, 2019).
lung carcinoma (4 papers, 2012 to 2023). "CCL1, CCL21, IP-10, CCL8 and CXCL9 levels were much higher in pleural effusions from patients with TP compared with lung cancer patients." (PMID 23028695, 2012). "Additionally, I-309/CCL1, macrophage inflammatory protein 1α (MIP-1α)/CCL3 and granulocyte colony-stimulating factor (G-CSF) from TAM increase CX3CL1 expression on lung cancer cells." (PMID 32466280, 2020).
tuberculosis (4 papers, 2021 to 2024). A chronic, recurrent infection caused by the bacterium Mycobacterium tuberculosis. "Subsequently, we further verified the transcription levels of genes on anti-tuberculosis-related genes such as CCL1, IL15, IL16, ISG15, GBP5, IL23, ATG2A, IFNβ, and CSF3." (PMID 38392218, 2024). "The expression levels of certain genes related to anti-tuberculosis were further confirmed, such as CCL1, IL15, IL16, ISG15, GBP5, IL23, ATG2A, IFNβ, and CSF3." (PMID 38392218, 2024). "Rv1476 overexpression inhibited the expression of some anti-tuberculosis-related genes, such as CCL1, IL15, IL16, ISG15, GBP5, IL23, ATG2A, IFNβ, and CSF3." (PMID 38392218, 2024). "CCL1 was shown to be upregulated upon in vitro infection with Mtb and in patients with active tuberculosis versus latently infected controls." (PMID 34253059, 2021). "Thus, a baseline chemokine signature of CCL1/CXCL1/CXCL10 could serve as an accurate biomarker for the diagnosis of pediatric tuberculosis." (PMID 34635070, 2021).
Granuloma (3 papers, 2008 to 2025). A compact, organized collection of mature mononuclear phagocytes, which may be but is not necessarily accompanied by accessory features such as necrosis. "In the lungs, CCL1 expression was up-regulated in Mycobacterium bovis purified protein derivative (PPD) induced granulomas." (PMID 19057661, 2008). "Increase of CCL1 was reported in the animal experimental model of granuloma by Mycobacterium." (PMID 27536524, 2016). "Since bacterial burden after BCG inoculation was not significantly different between two groups (text in the “Results” section), this enhanced formation of granuloma suggests the involvement of the hyper-response to biotic stimulus in CCL1 Tg mice, not due to reduced bacterial killing capacity." (PMID 27536524, 2016).
injury (3 papers, 2024 to 2025). Damage inflicted on the body as the direct or indirect result of an external force, with or without disruption of structural continuity. "In septic lung injury mice, Alkbh5 is highly expressed, promoting the demethylation of m6A on Ccl1 mRNA, thereby reducing the stability of Ccl1 mRNA and decreasing Ccl1 expression." (PMID 40254698, 2025). "While ENA-78 is involved in neutrophil chemotaxis, I-309 (CCL1) mediates monocyte chemotaxis and was decreased in trauma patients across all wound variables." (PMID 38903094, 2024). "In conclusion, we report a novel CCR8-antagonizing peptide that inhibited CCL1-driven intrahepatic monocytes infiltration and differentiation into pro-inflammatory phenotype, consequently ameliorating liver inflammation and fibrogenesis in an acute liver injury mouse model." (PMID 40486848, 2025).
multiple sclerosis (3 papers, 2017 to 2023). A progressive autoimmune disorder affecting the central nervous system resulting in demyelination. "In a mouse model of multiple sclerosis, high levels of CCL1 in the cerebrospinal fluid (CSF) are associated with increased B-cell and T-cell infiltration of CNS." (PMID 37765263, 2023). "This study also showed that CCL1 was upregulated by FOXP3+ Treg in the CNS in an EAE mouse model of multiple sclerosis, driving a feed-forward loop in which CCR8 expression was upregulated, in turn promoting Treg-mediated suppression of autoimmunity." (PMID 30024927, 2018).